CYLD (CYLD lysine 63 deubiquitinase)
Diseases named in the same sentence as CYLD in open-access papers (continued):
Sharing a sentence is not in itself a finding about the gene and the disease.
bladder cancer (4 papers, 2016 to 2024). "In this study, we found an onco-miRNA role for miR-130b in bladder cancer, and we revealed a potential scenario regarding its regulation, namely, that it sustained the activation of NF-κB signaling by decreasing the expression of the NF-κB inhibitor CYLD." (PMID 27391066, 2016). "Thus, the net result of NF-κB/miR-130b/CYLD signaling was probably the persistent activation of NF-κB, which could consequently compromise the progression of bladder cancer." (PMID 27391066, 2016). "Finally, we examined whether the relationships between NF-κB, miR-130b, and CYLD identified in bladder cancer cells were evident in vivo." (PMID 27391066, 2016). "Therefore, the NF-κB/miR-130b/CYLD axis could promote the progression of bladder cancer and could provide potential targets for cancer therapy." (PMID 27391066, 2016). "Finally, to support the notion that miR-130b maintains NF-κB activity by decreasing CYLD expression, we overexpressed or knocked down the expression of miR-130b in bladder cancer cells, and we confirmed the activation or suppression of NF-κB signaling, respectively." (PMID 27391066, 2016). "Thus, the present study revealed that, in bladder cancer, NF-κB can maintain its activity by establishing a feedback loop, in which NF-κB induced the expression of miR-130b, which consequently inhibited the expression of CYLD, which in turn was an endogenous inhibitor of NF-κB activation." (PMID 27391066, 2016).
oral squamous cell carcinoma (4 papers, 2019 to 2021). "For its part, the deubiquitination enzyme CYLD is capable of inducing different tumor suppressor pathways, and its overexpression inhibits SMAD7-mediated cell invasion in oral squamous cell carcinoma (OSCC)." (PMID 33498521, 2021).
Parkinson disease (4 papers, 2023 to 2026). A progressive degenerative disorder of the central nervous system characterized by loss of dopamine producing neurons in the substantia nigra and the presence of Lewy bodies in the substantia nigra and locus coeruleus. "Another study highlighted the conserved role of CYLD across species in regulating dopaminergic neuronal survival in Parkinson’s disease." (PMID 39945824, 2025). "In case of PARIS overexpression, a phenomenon observed in some Parkinson’s disease cases, CYLD knockdown restored mitochondrial survival within dopaminergic cells." (PMID 39945824, 2025). "The role of CYLD in other diseases such as Parkinson's disease, in which it has been shown to impact mitochondrial proteins in dopaminergic neurons, has brought interesting links to mitochondrial biogenesis." (PMID 37387450, 2023). "Similarly, the concomitant deletion of CYLD and Parkin increased the survival of mitochondria and dopaminergic neurons in both mouse and human embryonic stem cell models of Parkinson’s disease." (PMID 39945824, 2025). "In the context of the CNS, CYLD’s role in the regulation of NF-κB could have various implications and may contribute to NF-κB’s action in neurodegenerative and neuroinflammatory diseases such as Alzheimer’s, Parkinson’s, and multiple sclerosis." (PMID 39945824, 2025).
Anxiety (3 papers, 2023 to 2025). Intense feelings of nervousness, tension, or panic often arise in response to interpersonal stresses. "A previous study showed that CYLD regulates striatal network function, and plays an important role in striatal neuroinflammation; in addition, CYLD deficiency results in anxiety-like behavior." (PMID 36846565, 2023). "We have previously shown that CYLD modulates neuronal activity in the PNs of basolateral amygdala (BLA) and in the MSNs of the striatum and is critically involved in mediating anxiety-like behavior via activation of striatal microglia." (PMID 37241833, 2023).
basal cell carcinoma (3 papers, 2014 to 2016). A carcinoma involving the basal cells. "Recent work showed that TRAIP expression is increased in breast epithelial cell lines, in breast tumors, and in basal cell carcinomas (BCC) with a concomitant decrease in CYLD expression, a tumor suppressor interacting with TRAIP." (PMID 26369285, 2015).
cholesteatoma (3 papers, 2010 to 2023). A pathologic process characterized by the proliferation of keratinizing squamous epithelium resulting in the accumulation of keratin and cells in the middle ear and/or mastoid. "Previous reports indicated that reduced expression of CYLD in acquired cholesteatoma causes NF-κB activation, which contributes to excessive proliferation of keratinocytes." (PMID 33031450, 2020). "The precise mechanisms underlying the downregulation of CYLD in cholesteatoma remain to be elucidated." (PMID 20414373, 2010). "The mechanism was speculated as following; cytokines which were released from the cholesteatoma epithelium caused strong inflammation, resulting in high CYLD expression to suppress the inflammation." (PMID 33031450, 2020). "In addition, our results support the possibility that NF-κB activation accompanied by loss of CYLD may be an important step in the development and/or progression of cholesteatoma." (PMID 20414373, 2010). "In case inflammation around the cholesteatoma after removal was remained, CYLD expresses high to suppress inflammation." (PMID 33031450, 2020). "In contrast, in cholesteatoma, although CYLD expression was also observed in the cytoplasm of the spinous and granular layers, the expression levels were varied in the tissues of cholesteatoma patients." (PMID 33031450, 2020). "Another novelty of this study is that, contrary to our expectations, low CYLD expression in acquired cholesteatoma correlated with improved grade of otorrhea and shorter days to epithelialization." (PMID 33031450, 2020). "One of the novelties of this study is that, CYLD expression in acquired cholesteatoma tissue significantly correlated with the clinicopathological characteristic in patients with cholesteatoma." (PMID 33031450, 2020). "To determine the clinical significance of CYLD expression in cholesteatoma, we first performed immunohistochemical analysis of CYLD in the tissues obtained from 16 patients with acquired cholesteatoma." (PMID 33031450, 2020). "In recent studies, low CYLD expression has been reported in acquired cholesteatoma tissue and in several carcinomas, such as breast, oral, and liver." (PMID 33031450, 2020). "The relative expression levels of CYLD in cholesteatoma exhibited a significant correlation with the grade of otorrhea (R = 0.532, p = 0.039) and the period of epithelialization (R = 0.720, p = 0.002)." (PMID 33031450, 2020). "Next, we evaluated the clinical data of patients to determine the pathological significance of CYLD expression in cholesteatoma." (PMID 33031450, 2020). "Our immunohistochemical analysis revealed that CYLD expression levels were varied in the tissues of acquired cholesteatoma patients." (PMID 33031450, 2020). "It is necessary to investigate the mechanism by which CYLD expression in acquired cholesteatoma epithelium affects the prognosis after surgical removal of acquired cholesteatoma tissue." (PMID 33031450, 2020). "Further studies will focus on elucidating the detailed roles of CYLD expression in the pathogenesis of cholesteatoma." (PMID 33031450, 2020). "To determine the clinical significance of CYLD in acquired cholesteatoma, we evaluated CYLD expression in acquired cholesteatoma tissue by immunostaining and analyzed its correlation with clinicopathological characteristics." (PMID 33031450, 2020). "The percentage of area showing CYLD positive in RA skin epithelium was 19–62%, while that in cholesteatoma epithelium was 5–61%." (PMID 33031450, 2020). "The relative expression levels of CYLD in cholesteatoma exhibited a significant correlation with the grade of otorrhea (R = 0.532, p = 0.039)." (PMID 33031450, 2020). "The present study was performed to examine the possible role of CYLD expression in the pathogenesis of cholesteatoma." (PMID 20414373, 2010). "We found that CYLD reduced and activated increased NF-κB in cholesteatoma epithelium in comparison to RA skin." (PMID 20414373, 2010).
cholesteatoma (continued). "The percentage of CYLD-positive cells in cholesteatoma tissue was significantly lower as compared to paired normal RA skin (P = .022)." (PMID 20414373, 2010). "The results of the present study indicated that the level of CYLD expression was significantly downregulated in cholesteatoma in comparison with normal RA skin." (PMID 20414373, 2010). "Nevertheless, our data suggest the potential role of CYLD inactivation in cholesteatoma epithelium via multiple mechanisms, ranging from genetic alteration to epigenetic silencing." (PMID 20414373, 2010). "We found that CYLD expression was lower and activated NF-κB expression was higher in cholesteatoma epithelium in comparison to normal RA skin." (PMID 20414373, 2010). "We conducted immunohistochemistry to examine the expression of CYLD and NF-κB in 16 cases of cholesteatoma and paired cases of retroauricular (RA) skin." (PMID 20414373, 2010). "In cholesteatoma epithelium, activated NF-κB expression was significantly higher than in RA skin, whereas CYLD expression was significantly lower in cholesteatoma epithelium than in RA skin (P < .05)." (PMID 20414373, 2010). "To elucidate the role of CYLD in the expression of activated NF-κB in human cholesteatoma, we examined the correlation between CYLD and activated NF-κB expression in cholesteatoma." (PMID 20414373, 2010). "Using Pearson's correlation test, we found a significant inverse correlation between CYLD and activated NF-κB expression in cholesteatoma (r = −0.630, P = .007)." (PMID 20414373, 2010). "As a deubiquitinating enzyme, cylindromatosis (CYLD) was significantly downregulated in cholesteatoma and may be involved in cholesteatoma epithelial hyperplasia." (PMID 37609036, 2023). "Further investigation focusing on CYLD expression may contribute to elucidating the detailed molecular pathogenesis of cholesteatoma and open up new insights into improving the treatment of acquired cholesteatoma." (PMID 33031450, 2020). "Furthermore, we analyzed the relationship between CYLD expression level and clinicopathological characteristic in cholesteatoma." (PMID 33031450, 2020). "In this study, we evaluated CYLD expression in cholesteatoma tissue by immunostaining and assessed the clinical data of patients to determine the clinical significance of CYLD in acquired cholesteatoma." (PMID 33031450, 2020). "In addition, the relative expression level of CYLD in cholesteatoma tended to be lower in the group with recurrence, although it is not significant (p = 0.115)." (PMID 33031450, 2020). "Although it is still unclear whether NF-κB signaling is involved in the “recovery” of acquired cholesteatoma postoperatively, in brief, we speculated that high CYLD worked as suppressor of inflammation and low CYLD worked as initiator of wound healing." (PMID 33031450, 2020). "This indicated that CYLD expression in acquired cholesteatoma tissues may be an independent factor for recurrence in acquired cholesteatoma." (PMID 33031450, 2020). "Because it has been reported that CYLD expression is markedly up-regulated by inflammatory insults in middle ear, it is possible that CYLD expression was up-regulated in acquired cholesteatoma patients with strong inflammation postoperatively, resulting in otorrhea and slow recovery." (PMID 33031450, 2020). "Specifically, we were interested in whether CYLD expression is altered in cholesteatoma and whether CYLD expression level affects the activity of NF-κB in cholesteatoma." (PMID 20414373, 2010). "Furthermore, a significant inverse correlation was detected between CYLD and activated NF-κB expression in cholesteatoma epithelium (r = −0.630)." (PMID 20414373, 2010). "The inverse correlation between CYLD and activated NF-κB in cholesteatoma may be involved in cholesteatoma epithelial hyperplasia." (PMID 20414373, 2010). "In the cholesteatoma tissue, CYLD expression was seen in a few cells in the basal layer." (PMID 20414373, 2010).
cholesteatoma (continued). "Moreover, a study revealed that the level of CYLD expression in acquired cholesteatoma is significantly correlated with the clinicopathological characteristics, including wound healing, infection, and recurrence in cholesteatoma patients." (PMID 37609036, 2023). "In this study, we revealed the possibility that CYLD expression in acquired cholesteatoma correlates with clinicopathological characteristics, especially progression preoperatively and prognosis including infection, wound healing and recurrence in cholesteatoma patients." (PMID 33031450, 2020). "In addition, the present findings suggested that downregulation of CYLD expression, which is highly expressed in normal skin, may be involved in the pathogenesis of human cholesteatoma." (PMID 20414373, 2010). "We hypothesized that CYLD may be involved in the NF-κB signaling pathway and that the inverse correlation between CYLD and activated NF-κB level may be related to the mechanism of cellular hyperplasia in cholesteatoma epithelium." (PMID 20414373, 2010). "We hypothesized that CYLD may regulate the NF-κB signaling pathway in cholesteatoma." (PMID 20414373, 2010). "Therefore, investigation of CYLD expression may be a key step to understanding the cellular survival or hyperplasia in cholesteatoma epithelium." (PMID 20414373, 2010). "In case we focused on the correlation with the presence or absence of recurrence, the relative expression level of CYLD in cholesteatoma tended to be lower in the group with recurrence, although it was not significant (p = 0.115)." (PMID 33031450, 2020). "While, in case inflammation around the cholesteatoma after removal was not remained, low CYLD expression decreased keratinocyte differentiation, and increased proliferation (i.e. wound healing)." (PMID 33031450, 2020). "We found a significant inverse correlation between CYLD and NF-κB in cholesteatoma, suggesting that NF-κB activation is inhibited in cases with normal CYLD function but that it tends to be overexpressed in the absence of functional CYLD." (PMID 20414373, 2010). "In addition, CYLD negatively regulates RANK signaling, which is known to be a key factor in bone resorption in cholesteatoma." (PMID 20414373, 2010). "In addition to the critical role of CYLD in the NF-κB pathway, CYLD has the ability to function as a negative regulator of the JNK signaling pathway, which plays an important role in cell survival in human cholesteatoma." (PMID 20414373, 2010). "CYLD also negatively regulates the c-Jun N-terminal kinase (JNK) signaling pathway and mitogen-activated protein kinase (MAPK) pathway, which are known to participate in a wide range of cellular processes, including proliferation, differentiation, and apoptosis of cholesteatoma." (PMID 20414373, 2010).
inflammatory bowel disease (3 papers, 2020 to 2024). A spectrum of small and large bowel inflammatory diseases of unknown etiology. "Furthermore, CYLD polymorphisms were specifically associated with inflammatory bowel disease (IBD) that comprised 2320 patients with Crohn’s disease." (PMID 32882786, 2020). "Therefore, the role of CYLD in inflammatory bowel disease has also received attention from researchers." (PMID 34956195, 2021). "Interestingly, in people with inflammatory bowel disease, CYLD expression was reduced." (PMID 39403278, 2024).
lung adenocarcinoma (3 papers, 2016 to 2020). A carcinoma that arises from the lung and is characterized by the presence of malignant glandular epithelial cells. "The proapoptotic activity of lysine 63 deubiquitinase (CYLD) was inhibited due to overexpressed microRNA-197 in lung adenocarcinoma cells." (PMID 31717720, 2019). "In the 6 surgical specimens from the patients diagnosed with lung adenocarcinoma, CYLD expressions were detected in both lung adenocarcinoma tissues and peritumoral tissues." (PMID 27738385, 2016).
neuroblastoma (3 papers, 2016 to 2026). Neuroblastoma (NB) is the most common solid, extracranial childhood tumor. "We observed that a short ATRA treatment of neuroblastoma causes a transient SUMOylation of CYLD that reduces its deubiquitin activity, as well as activation of NF-κB signaling via ubiquitination of TRAF2/TRAF6." (PMID 26973854, 2016). "Furthermore, high CYLD expression is associated with better overall and relapse-free survival and inversely correlated with the stage of neuroblastoma." (PMID 26973854, 2016). "Recently, we have demonstrated a significant role of CYLD in differentiation of neuroblastoma." (PMID 26973854, 2016). "In this context, maintaining high expression levels of CYLD and SUMO proteins together can be used promising tools for future therapeutic strategies for neuroblastoma patients." (PMID 26973854, 2016). "Therefore, it was proposed that the balance between non-SUMOylated and SUMOylated CYLD can direct neuroblastoma cancer cells against differentiation or cell death via regulation of NF-κB signaling." (PMID 26973854, 2016).
osteoporosis (3 papers, 2014 to 2024). A condition of reduced bone mass, with decreased cortical thickness and a decrease in the number and size of the trabeculae of cancellous bone (but normal chemical composition), resulting in increased fracture incidence. "More specifically, CYLD was found to inhibit RANK-induced signaling by deubiquitinating TRAF6, and its physiological importance is reflected by the fact that CYLD-deficient mice develop osteoporosis, due to accelerated osteoclastogenesis." (PMID 30513612, 2018). "It has been demonstrated that TRAF6-mediated RANK signaling in pre-OCs is negatively regulated de-ubiquitinase CYLD, and that CYLD-deficient mice exhibit osteoporosis due to increased OC activity." (PMID 25368616, 2014). "CYLD mitigates NLRP3 inflammasome-triggered pyroptosis in osteoporosis through its deubiquitination of WNK1." (PMID 38561786, 2024).
Ovarian Tumour (3 papers, 2015 to 2016). "CYLD is a K63- and M1-specific DUB; and vOTU is an ovarian tumor (OTU) domain-containing DUB from Crimean-Congo hemorrhagic fever virus (CCHFV) large (L) protein that can cleave all kinds of Ub linkages except M1 linkage." (PMID 27082114, 2016). "To test this hypothesis we performed SRLM on U2OS cells transfected with plasmids expressing the de-ubiquitinases (DUBs) CYLD, (cylandromatosis DUB) or OTULIN (ovarian tumour DUB with linear linkage specificity; also known as FAM105B)." (PMID 27586688, 2016). "These 33 enzymes represent >1/3 of all known human DUBs, and they include members of all four major DUB families—20 USPs (including CYLD, USP14 an USP8), 8 Ovarian Tumour (OTU) deubiquitinases (including Trabid and Cezanne), 3 ubiquitin C-terminal hydrolases (UCHs) and 2 JAMM metalloproteases." (PMID 25907794, 2015).